SRD5A1 (steroid 5 alpha-reductase 1)
Diseases named in the same sentence as SRD5A1 in open-access papers (continued):
Sharing a sentence is not in itself a finding about the gene and the disease.
multiple myeloma (1 paper, 2021). "Meanwhile, the autophagy inhibitor (3-methyladenine) and SRD5A1 inhibitor (Dutasteride) were utilized to evaluate their anti-myeloma effect." (PMID 33627630, 2021). "Furthermore, we validated that Dutasteride, an SRD5A1 inhibitor, induced myeloma cells apoptosis in human myeloma cells and xenograft mouse models." (PMID 33627630, 2021). "Steroid 5α-reductase type I (SRD5A1) is a validated oncogene in many sex hormone-related cancers, but its role in multiple myeloma (MM) remains unknown." (PMID 33627630, 2021). "To determine whether SRD5A1 functions as an oncogene in MM, we functionally knocked down SRD5A1 in myeloma cells by expressing the lentivirus-mediated SRD5A1-shRNA which was under the control of a doxycycline (Dox)-inducible gene promoter thus avoiding the adverse effect of long-term knockdown." (PMID 33627630, 2021). "Nonetheless, neither testosterone nor DHT has an impact on myeloma cell proliferation in this study (data not shown), but we did find that varying levels of SRD5A1 could alter the growth of myeloma cells." (PMID 33627630, 2021).
ovarian carcinoma (1 paper, 2025). A malignant neoplasm originating from the surface ovarian epithelium. "Our investigation revealed that TWP’s efficacy is driven by its ability to modulate five core targets—EGFR, JAK1, JAK2, PTPN11, and SRD5A1—which our analysis showed to be dysregulated in clinical ovarian cancer datasets." (PMID 41181611, 2025). "Through integrated network analysis and clinical transcriptomic data, we identified five core targets (EGFR, JAK1, JAK2, PTPN11, and SRD5A1) that are differentially expressed in ovarian cancer tissues and serve as central nodes in TWP’s mechanism of action." (PMID 41181611, 2025). "Similarly, TWP’s suppression of SRD5A1 may attenuate androgen signaling, which contributes to progression in a significant subset of ovarian cancers, offering a novel strategy to counteract hormone-mediated chemoresistance." (PMID 41181611, 2025).
ovarian endometriosis (1 paper, 2016). A non-neoplastic disorder characterized by the growth of endometrial tissue in the ovaries. "SRD5A1 and SRD5A2 can convert both P to 5α-dihydroprogesterone in human ovarian endometriosis and T to 5α-dihydrotestosterone in human prostate, while the function of SRD5A3 in steroid metabolism is still unclear." (PMID 27149376, 2016).
preeclampsia (1 paper, 2024). Preeclampsia is a hypertensive disorder of pregnancy that is characterized by new-onset hypertension with proteinuria presenting after 20 weeks of gestation, and depending on mild or severe forms may initially present with severe headache, visual disturbances, and hyperreflexia. "We identified CYP17A1, HSD17B3, SRD5A1, CYP19A1, CYP11B1, HSD11B1 and HSD11B2 as potentially affected enzymes in preeclampsia." (PMID 39684415, 2024). "In the next step of the gonadal steroid metabolism catalyzed by SRD5A1, the ratio of testosterone to DHT was significantly increased in preeclamptic women compared to controls, which may be a consequence of the reduced conversion of testosterone to DHT in the previous step in preeclampsia." (PMID 39684415, 2024).
prostate tumor (1 paper, 2013). "We however found high expression levels of certain steroidogenic enzymes; SRD5A1, AKR1C2, AKR1C3, and HSD17B10, in bone metastases when compared to non-malignant prostate and primary prostate tumor tissue." (PMID 24244276, 2013).
tumor (15 papers, 2011 to 2025). "Consistent with this, reanalysis of the TCGA PRAD cohort (n = 497) showed that tumor T-stage progression was associated with SRD5A1 and HSD17B3 gene amplification and gain, but shallow or deep deletion of SHBG and HSD17B2 genes." (PMID 34298692, 2021). "SRD5A1, on the other hand, remained unchanged in low-grade EC compared to tumor-adjacent endometrium." (PMID 39205690, 2024). "Subsequently, we examined tumor growth and migration in SRD5A1 knockdown BCa cells and found a significant clinical therapeutic role of 5α-reductase inhibition for the treatment of BCa." (PMID 36800968, 2023). "Although gene expression levels were lower with OB diets, higher body weight at tumor detection increased the expression of intratumoral srd5a1 (p = 0.023) and srd5a2 (p = 0.001)." (PMID 34535690, 2021). "A significant correlation between SRD5A1 mRNA expression of the primary tumor tissue and clinical benefit was found." (PMID 31745978, 2020). "For primary tumor tissue (n = 23), the SRD5A1 expression levels and AR pathway activity scores were higher in patients with clinical benefit, but significance was lost (p = 0.57 and p = 0.20, respectively)." (PMID 31745978, 2020). "Steroid 5α-reductase type I (SRD5A1), as an important part of the steroid metabolism, converts testosterone to dihydrotestosterone and regulates sex hormone levels, which accommodates tumor occurrence or development." (PMID 32983992, 2020). "It has been documented that dutasteride exerts specific molecular actions on tumor cell biology via inhibiting SRD5A1, thereby reducing the incidence of PC." (PMID 32983992, 2020). "Both finasteride (SRD5A1 inhibitor) and dutasteride (dual SRD5A1/SRD5A2 inhibitor) have been shown in chemoprevention trials to give rise to a reduction in tumor incidence but also cause an increase in high-grade disease as determined by Gleason grade." (PMID 35582223, 2020). "Our results suggest that SRD5A1 is an oncogenic player in BCa, and 5α-reductase inhibition may decrease and control tumor growth in patients with BCa." (PMID 36800968, 2023). "We then compared tumor cell growth between control (Scr) and SRD5A1-silenced T24 and J82 cells." (PMID 36800968, 2023). "The important role of SRD5A1 in SDC tumor proliferation leads to the hypothesis that blocking this key enzyme in intratumoral steroidogenesis using the 5α-reductase-1 inhibitor dutasteride could be beneficial." (PMID 34298742, 2021). "Thus, the probability of activity of seven tumor-driving pathways and expression levels of SRD5A1 mRNA were quantified." (PMID 34298742, 2021). "We hypothesize that high levels of SRD5A1 mRNA in SDC tissue are indicative of a high dependency on AR signaling for tumor proliferation, as well as that the deprivation of circulating androgens will hit these tumors hard, resulting in a better prognosis upon CAB treatment." (PMID 34298742, 2021). "Furthermore, it would be interesting to evaluate the prognostic value of AR‐pathway activity and SRD5A1 expression, as the survival differences may also be a result of a more indolent (well‐differentiated) tumor." (PMID 31745978, 2020). "Therefore, we suspected that SRD5A1 might regulate tumor progression and metastasis via NF-κB/VEGF signaling pathway." (PMID 32983992, 2020). "Using the GEPIA2 database, we compared tumor tissues from TCGA with normal tissues from GTEx and found that SRD5A1, FUT8, and HES6 were significantly overexpressed in tumor tissues." (PMID 40729369, 2025). "Several enzymes related to androgen biosynthesis and (re-)activation were highly expressed in all tumor biopsy samples, including HSD17B10, STS, SRD5A1, AKR1C3, and HSD11B2." (PMID 33974560, 2021). "TP led to reduced tumor growth, intratumoral inflammation, and intratumoral androgen-regulated gene expression (srd5a1, srd5a2) when incorporated with the CON diet but greater tumor growth and intratumoral gene expression when incorporated with the OB diet." (PMID 34535690, 2021).
tumor (continued). "Moreover, mRNA expression of 5α-reductase (SRD5A1), which converts T into the more active metabolite DHT, was higher (2.14-fold) in the cell-like tumor cell line." (PMID 39456756, 2024). "Indeed, the main finding of our study is that SRD5A1 and SRD5A2 decreased and SRD5A3 significantly increased in HCC tumor tissues." (PMID 36159555, 2022). "After adjusting for body weight at tumor detection, OB diets did not affect srd5a1 expression but led to significantly lower intratumoral srd5a2 (p = 0.0004) and ar (p = 0.032) expression compared with CON diets." (PMID 34535690, 2021). "SRD5A1 expression levels and AR pathway activity scores were not significantly different between primary tumor tissue, lymph node metastatic tissue and distant metastatic tissue." (PMID 31745978, 2020). "To understand the clinical outcome of SRD5A1 expression, we examined the data about multiple cancers from the Cancer Genome Atlas (TCGA) using GEPIA online tool with customizable functional analysis, such as tumor/normal differential gene profiling and patient survival analysis." (PMID 33627630, 2021).
cancer (8 papers, 2012 to 2023). A tumor composed of atypical neoplastic, often pleomorphic cells that invade other tissues. "Therefore, we focused on the anti-oncogenic effects of 5α-reductase inhibition and evaluated the effects on cancer progression of the dutasteride target genes SRD5A1 and SRD5A2, encoding 5α-reductase Type 1 and 2, respectively." (PMID 36800968, 2023). "The expression of SRD5A1 was slightly downregulated in the cancer tissues relative to those within normal tissues." (PMID 36159555, 2022). "As one example of a gene in the 80-gene signature perhaps understudied in the context of cancer, SRD5A1 (steroid 5 alpha-reductase 1 gene), involved in progesterone metabolism, showed an association of nearby SV breakpoints with increased expression." (PMID 34788622, 2021). "Since irreparable structural mutations in cells may result in cancer occurrence, we then determined the genetic alterations of SRD5A3, DOLK, SRD5A1, and HSD17B3 in BC." (PMID 34465365, 2021). "SRD5A1 also showed associations with worse patient survival in terms of both breakpoint patterns and expression for POG570 and worse survival associations for multiple external pan-cancer datasets, including TCGA." (PMID 34788622, 2021). "As mounting evidence points to the regulatory role of AR in cancer cellular senescence, we determined whether SRD5A1 might act as a moderator for CRC cellular senescence." (PMID 32983992, 2020). "In all paired cases, SRD5A1 was expressed at a higher level in the cancer than in the NAT samples." (PMID 22257483, 2012). "Given all that, these results support the point that SRD5A1 knockdown-induced apoptosis could be aggravated by 3-MA mediated autophagy inhibition in MM cells, which could be applied as a novel therapeutic notion for cancer treatment." (PMID 33627630, 2021).
adenocarcinoma (1 paper, 2012). A common cancer characterized by the presence of malignant glandular cells. "Comparison of the signal intensities showed a 3.3- and 6.3-fold stronger signal of SRD5A1 mRNA in adenocarcinoma and SCC of the lung, respectively, when compared to NAT." (PMID 22257483, 2012).
lung (1 paper, 2012). "The conduction of similar experiments in cell lines originating from lung SCC is planned (e.g. in NCI-H520 or SW-900 cells), since an up-regulation of SRD5A1 has been observed in tissue samples of SCC as well." (PMID 22257483, 2012).
SRD5A1 also shares sentences with these, for which no sentence is quoted: endometrial cancer (2 papers); acute myeloid leukemia (1); cardiac hypertrophy (1); gastric cancer (1); germ cell tumor (1); glioblastoma multiforme (1); Hirsutism (1); infection (1); liver disease (1); major depressive episode (1); mesothelioma (1); metastatic tumors (1); pancreatic adenocarcinoma (1); prostatic hyperplasia (1); seminoma (1); Simpson-Golabi-Behmel syndrome (1); teratoma (1).